ZBTB8A (zinc finger and BTB domain containing 8A)
Description:
May be involved in transcriptional regulation.
Synonyms: BOZF1; FLJ90065; ZNF916A; ZBTB8
Tractability: PROTAC: UniProt records ubiquitination sites on it; ubiquitination databases record sites on it.
Gene: Protein-coding gene on chromosome 1 (32,539,142 to 32,605,941, forward strand). Ensembl gene ENSG00000160062.
Subcellular location: Nucleus
Subcellular location (Human Protein Atlas): Focal adhesion sites; Nuclear speckles
Gene Ontology:
Molecular function: DNA-binding transcription repressor activity, RNA polymerase II-specific; protein binding; RNA polymerase II-specific DNA-binding transcription factor binding; transcription cis-regulatory region binding; transcription coactivator binding; DNA-binding transcription factor activity, RNA polymerase II-specific; RNA polymerase II cis-regulatory region sequence-specific DNA binding
Biological process: negative regulation of transcription by RNA polymerase II; regulation of transcription by RNA polymerase II
Cellular component: nucleus
Genetic constraint (gnomAD): Loss-of-function variants: 19 observed, 38.79 expected, observed/expected ratio (o/e) 0.49, 90% interval 0.34 to 0.72. The upper end of that interval is the gene's LOEUF score, 0.72, which puts it in group 2 of 6, group 1 being the genes least tolerant of losing a copy. Missense variants: 394 observed, 564.49 expected, observed/expected ratio (o/e) 0.7, 90% interval 0.64 to 0.76. Synonymous variants: 181 observed, 196.54 expected, observed/expected ratio (o/e) 0.92, 90% interval 0.81 to 1.04.
Homologues: Orthologues: chimpanzee ZBTB8A (99% identical), macaque ZBTB8A (98% identical), dog ZBTB8A (95% identical), pig ZBTB8A (95% identical), guinea pig ZBTB8A (91% identical), rabbit ZBTB8A (90% identical), mouse Zbtb8a (83% identical), rat Zbtb8a (83% identical), tropical clawed frog zbtb8a (50% identical), tropical clawed frog zbtb8a.2 (47% identical), zebrafish zbtb8a (44% identical). Paralogues in human: ZBTB8B (36% identical), ZBTB10 (31% identical), ZBTB22 (20% identical), ZBTB9 (17% identical), C17orf113 (14% identical).
Diseases named in the same sentence as ZBTB8A in open-access papers:
ZBTB8A is named in the same sentence as 4 diseases in open-access papers, as found by Europe PMC text mining. Sharing a sentence is not in itself a finding about the gene and the disease. The quoted sentences say what the papers report.
sialadenitis (1 paper, 2013). Sialadenitis is an infection of the salivary glands. "A difference in Zbtb8a and Ccdc28b expression between the NOD and B10 alleles was previously reported in the salivary glands in a model of sialadenitis." (PMID 23934554, 2013).
ZBTB8A also shares sentences with these, for which no sentence is quoted: breast carcinoma (1 paper); cancer (1); diabetes insipidus (1).